DCTPP1 (dCTP pyrophosphatase 1)
Diseases named in the same sentence as DCTPP1 in open-access papers (continued):
Sharing a sentence is not in itself a finding about the gene and the disease.
cancer (continued). "Recent research has suggested that DCTPP1 may play a critical role in mediating chemotherapy resistance in cancer." (PMID 39200195, 2024). "Therefore, the effects of DCTPP1 and QPRT on DNA function are probably associated with their cancer-promoting effects." (PMID 32716908, 2020). "QPRT and DCTPP1 have been reported, but only in a few types of cancers." (PMID 32716908, 2020). "Therefore, the role of DCTPP1 in cancer progression and drug resistance is particularly noteworthy." (PMID 39200195, 2024). "Modulation of DCTPP1 activity might be a valuable tool to disrupt de novo synthesis and nucleotide homeostasis in highly proliferative cells with a great demand for DNA precursors such as cancer cells." (PMID 31377845, 2020). "Given the high rates of DCTPP1 gene amplifications observed in BRCA, we analyzed its mRNA expression levels across tumor grades and cancer stages in BRCA cases." (PMID 39200195, 2024). "In TCGA-BRCA database, DCTPP1, SLC27A2, and IFNG were highly expressed in cancer tissues, while MYH3 was expressed at a low level in cancer tissues." (PMID 38753091, 2024). "For instance, stauprimide treatment, which suppresses MYC transcription in various cancer cell lines, induces selective down-regulation of MYC target genes including DCTPP1." (PMID 31377845, 2020). "DCTPP1 inhibition also appears to have a negative impact on the survival and tumor malignancy of cancer cells." (PMID 35223993, 2022). "The overexpression observed in MCF7 and T47D suggest that DCTPP1 may serve as a potential biomarker for predicting chemotherapy response in ER-positive, luminal A BRCA cases, highlighting its potential utility in this cancer subtype." (PMID 39200195, 2024).
tumor (11 papers, 2014 to 2025). "Research on the coding gene DCTPP1, is currently focused on exploring its complex association with tumor cells." (PMID 40849295, 2025). "Loss of DCTPP1 expression resulted in a significant delay in tumor growth, where the difference in tumor volume was statistically significant after 6 weeks (p < 0.05)." (PMID 35223993, 2022). "Additionally, DCTPP1 is also believed to be potentially associated with the development of certain tumours and treatment resistance, although the exact mechanisms remain unclear and require further investigation to elucidate its role in disease." (PMID 38686496, 2024). "Scientists are increasingly interested in DCTPP1 because it exhibits unique expression patterns and functional properties in various tumor cells." (PMID 40849295, 2025). "To investigate the role of DCTPP1 in human tumors, we used publicly available gene expression databases to compare mRNA transcript abundance between tumor and matched normal tissue specimens." (PMID 39200195, 2024). "DCTPP1, as a dCTP pyrophosphatase, is believed to play a role in inhibiting the excessive accumulation of ROS in tumour cells by clearing aberrant nucleotides." (PMID 38686496, 2024). "Collectively, our analyses reveal that DCTPP1 is up-regulated across all tumor grades and stages in BRCA, at both mRNA and protein levels." (PMID 39200195, 2024). "This analysis corroborated the significant up-regulation of DCTPP1 mRNA in tumor tissues compared to controls (p-value = 1.67 × 10−57)." (PMID 39200195, 2024). "As mounting evidence indicates that PIK3/Akt pathway always plays a crucial role in tumour growth, DCTPP1 deletion in both SKOV3 and OVCAR8 cells resulted in an elevated level of p21 and, at the same time, a decreased level of pAkt/Akt." (PMID 35223993, 2022). "A xenograft tumor mouse model was established to identify the impact of DCTPP1 on tumour growth in vivo." (PMID 35223993, 2022). "Ki67, a marker of tumour proliferation, was also observed to be decreased in DCTPP1 knockdown groups by immunohistochemistry." (PMID 35223993, 2022). "It was notable that although DCTPP1 was detectable in both the nucleus and cytoplasm in cancerous tissues, positive signals of DCTPP1 were mainly localized in the nucleus of tumor cells." (PMID 26075750, 2015). "The apparent dual roles of DCTPP1 pro-tumor in some contexts yet protective in trophoblasts may indeed reflect tissue-specific functions." (PMID 40849295, 2025). "At 6 weeks, DCTPP1-siRNA tumor weights were significantly lighter than control tumors." (PMID 34113564, 2021). "Our analysis revealed low DCTPP1 levels in DCTPP1-siRNA tumor tissue relative to control tissue." (PMID 34113564, 2021). "A tumor xenograft assay demonstrated the tumor-promoting effects of the DCTPP1 and QPRT genes." (PMID 32716908, 2020). "We have used QuPath32 quantitative image analysis of DCK and DCTPP1 expression in tumour tissue biopsies from a Phase I patient cohort treated with NUC-1031 (ref.1), involving the fast and interactive training of object classifiers using machine learning techniques." (PMID 31113993, 2019). "Higher DCTPP1 expression was related to higher tumor stage (P=0.001) and tumor grade (P=0.018)." (PMID 26075750, 2015). "Moreover, DCTPP1-siRNA tumor volume growth was slower relative to control tumors." (PMID 34113564, 2021). "Interestingly, the correlation between DCTPP1 expression and MDR1 expression was more significant in GC samples with high tumor grade (n = 14, r = 0.860, P < 0.0001)." (PMID 27612427, 2016).
DCTPP1 also shares sentences with these, for which no sentence is quoted: breast tumor (1 paper); COVID-19 (1); leprosy (1).